LOX (lysyl oxidase)
Diseases named in the same sentence as LOX in open-access papers (continued):
Sharing a sentence is not in itself a finding about the gene and the disease.
breast carcinoma (continued). "The aminomethylenethiophene scaffold-bearing inhibitor CCT365623 is a dual LOX/LOXL2 inhibitor that can suppress breast cancer growth and metastasis." (PMID 35331296, 2022). "In agreement with these cell-based findings, in vivo studies have demonstrated a role for LOX in the regulation of breast cancer progression and metastasis." (PMID 35804902, 2022). "Because these cells are low in E-cadherin expression, it is still unclear how modulation of cadherin-based cell-cell contacts contribute to lysyl oxidase-dependent collective invasion in ductal-type breast cancer." (PMID 35292774, 2022). "Treatment with LOX inhibitors in pre-clinical breast cancer models has been highly effective to increase drug penetration." (PMID 35267548, 2022). "Lastly, in a clinically relevant metastatic breast carcinoma model, LOX inhibition counteracted the metastasis-promoting, ECM-related effects of PTX." (PMID 34666995, 2022). "On the other hand, in breast cancer, the most frequent metastatic sites are the bone and the lung, and LOX has been proposed to play an essential role in the development of the premetastatic niche in those specific organs." (PMID 36497411, 2022). "In a pre-clinical model of breast cancer, enhanced collagen expression and stabilization by LOX led to elevated tumor hypoxia, malignant signaling, and dysregulated angiogenesis." (PMID 35435599, 2022). "Interleukin-1β (IL-1β) and hypoxia-induced lysyl oxidase (LOX) are two other examples of primary tumour-derived soluble factors able to promote the colonisation of cancer cells in models of breast cancer bone metastasis." (PMID 36612237, 2022). "Increased hypoxia-induced LOX secretion is correlated with increased bone metastasis in ER-breast cancer." (PMID 36497411, 2022). "We next investigated the role of LOX in chemotherapy-induced metastasis in a clinically relevant breast carcinoma model." (PMID 34666995, 2022). "In breast cancer, LOX enzymes are upregulated as a response to hypoxia to various degrees depending on the tumor type." (PMID 36140753, 2022). "ATP7A silencing attenuates LOX activity and represses the growth and metastasis of mouse lung and breast cancer cells." (PMID 36293126, 2022). "Responses to paclitaxel-based therapy in breast cancer models induced LOX levels and activity in the lungs, resulting in pulmonary ECM remodeling and a pro-metastatic niche." (PMID 35205728, 2022). "Under hypoxic conditions, LOX is overexpressed and promotes the metastasis and invasion of breast cancer cells." (PMID 36232621, 2022). "Intraperitoneal injection of LOX inhibitors in mice significantly reduces the metastatic foci of breast cancer in both soft tissue and skeletal sites in the early stage of metastasis." (PMID 36293126, 2022). "The LOX-PP binding interaction with CIN85 at this site inhibits the invasive phenotype of breast cancer cells on Matrigel and the collagenolytic activity of transfected cells plated on a collagen substrate." (PMID 35563478, 2022). "Conversely, expression of either full-length LOX or the catalytically active peptide was sufficient to enhance the migratory and adhesive capacity of poorly invasive breast cancer cells." (PMID 35804902, 2022). "In order to identify biological functions that are unique to LOX in breast cancer cells, we have knocked out the five lysyl-oxidase genes in MDA-MB-231 breast cancer cells using CRISPR/Cas9." (PMID 36232621, 2022). "Their report about LOX expression in canine mammary tumors (CMT), revealed that lysyl oxidase expressed as His-tagged fusion protein in prokaryotic expression vector was used for detection of circulating protein LOX in serum of CMT subjects." (PMID 35189882, 2022). "Reduction of the tumor tissue stiffness by application of matrix cross-linking enzyme lysyl oxidase (LOX) significantly reduce blood vessel formation in a mouse model of spontaneous mammary tumors." (PMID 36419159, 2022).
breast carcinoma (continued). "The secretion of LOX was reported to induce the formation of a pre-metastatic niche in preclinical breast cancer models." (PMID 34930321, 2021). "Collagen deposition and stabilization in the lungs through activity of lysyl oxidase has been shown to promote breast cancer cell metastatic colonization." (PMID 33670906, 2021). "Hypoxic breast cancer cells produce multiple members of the lysyl oxidase (LOX) family, including LOX, LOXL2, and LOXL4, in a HIF-1-dependent manner." (PMID 33777815, 2021). "In a biomimetic 3D model technology of hypoxia-driven cancer progression, it was found that LOX is the most up-regulated marker in the model, and LOX has prognostic significance for breast cancer patients." (PMID 34595188, 2021). "LOX depends on copper in order to function, and LOX is encompassed in extracellular processes that facilitate breast cancer cell movement." (PMID 34988012, 2021). "Individual cell migration is an early step in breast cancer metastasis; thus, ATOX1 silencing decreases the breast cancer cell migration velocity via coordinated copper transport in the ATP7A-LOX (proenzyme of lysyl oxidase) axis." (PMID 34504870, 2021). "Taken together, these results confirm the positive correlation between OSM signaling and lysyl oxidase mRNA expression in breast cancer patients." (PMID 34011405, 2021). "In vivo, MIA PaCa-2 pancreatic cancer and NF639 breast cancer cells showed reduce tumour weight after injection into nude mice followed by injection of recombinant LOX pro-peptide, or when infected with a LOX pro-peptide over-expressing virus." (PMID 33513979, 2021). "We performed the same correlation analysis as above, but instead focused on OSMR and lysyl oxidase mRNA expression in breast cancer patients." (PMID 34011405, 2021). "Overexpression of LOX in 4T1 breast cancer cells has been shown to increase activation of p38 MAPK signaling and was associated with greater cell invasion." (PMID 33513979, 2021). "Pre-clinical studies in vivo of the aminomethiophene based LOX inhibitor CCT365623 showed inhibition caused delayed tumour development and reduced lung metastasis in mouse breast cancer models." (PMID 33513979, 2021). "Specific targeting of LOX enzymes for the treatment of breast cancer and metastases seems to offer a significant promise with reduced risk." (PMID 33669630, 2021). "Previous studies reported that high LOX expression is associated with poor survival of triple-negative breast cancer, and silencing LOX can induce breast cancer cell apoptosis and reduce its chemotherapy resistance." (PMID 34595188, 2021). "Using a murine model of breast cancer, it was demonstrated that LOX expression was stimulated by TGF-β derived, in this case, from epithelial origin, which generates a stiffer collagen matrix that stimulates tumoral progression." (PMID 33946660, 2021). "The expression of LOX correlates in breast cancer, provides strong preclinical rationale for developing LOX inhibitors for intervention in chemo-resistant triple negative breast cancer." (PMID 35054220, 2021). "Secretion of lysyl oxidase (LOX) by primary breast cancer cells under hypoxic conditions has been shown to modulate the ECM at bone metastatic sites to create a pre-metastatic niche." (PMID 34831167, 2021). "Despite the different clinical trials focused on LOX inhibitors, clinical data in breast cancer remain essentially inexistent." (PMID 33669630, 2021). "Implying therapeutic potential, the silencing LOX reduces the metastatic spread of breast carcinoma cells." (PMID 34988012, 2021). "The LOX gene is abnormally expressed in a variety of tumors, such as breast cancer, pancreatic cancer, colorectal cancer, hepatocellular carcinoma, and esophageal squamous cell carcinoma." (PMID 34595188, 2021). "LOX is known as an enzyme that crosslinks extracellular matrix proteins such as collagen and promotes breast cancer metastasis, and the release of LOX is regulated by HIF-1α." (PMID 33126606, 2020).
breast carcinoma (continued). "Our previous study also reported that the expression of HIF-1α, leading to the secretion of lysyl oxidase (LOX), is increased in the highly metastatic breast cancer cells MDA-MB-231." (PMID 33126606, 2020). "Secretion of lysyl oxidase (LOX) from primary breast carcinoma cells induced osteoclast differentiation and osteolytic skeletal lesion formation in animal tumor models." (PMID 32637413, 2020). "Among other factors, breast cancer cells in the primary tumor secrete lysyl oxidase (LOX) that regulates fibronectin activity and matrix remodeling." (PMID 32232008, 2020). "Analysis of LOX expression in a panel of breast cancer cell lines demonstrated that TNBC cells express relatively higher levels of LOX." (PMID 32415208, 2020). "Previous studies have shown that hypoxia in breast cancer induces tissue stiffness through the involvement of lysyl oxidase, which promotes collagen crosslinking." (PMID 33256820, 2020). "Adipocytokines such as TNF-α, IL-1β, FGF-2, and CCL2, have been found to increase LOX expression in breast cancer." (PMID 33123472, 2020). "Adipocytokines such as TNF-α, IL-1β, FGF-2, and CCL2 have also been found to be involved in the regulation of LOX expression in breast cancer." (PMID 33123472, 2020). "It has been demonstrated that the ECM modifying enzyme LOX secreted by breast cancer cells induces a metastatic niche in bone." (PMID 33123472, 2020). "Small molecule LOX inhibitors reduced angiogenesis and growth in experimental breast cancer and led to decreased metastases in lung and liver." (PMID 32466266, 2020). "The extracellular function of the canine LOX along with their elevated mRNA and protein expression in canine mammary tumors makes LOX a therapeutic target for diagnosis of mammary tumors." (PMID 32542505, 2020). "MSCs can also promote EMT by the different mechanism of producing hyaluronan which enables MSCs to make CD44-expressing breast cancer cells produce lysyl oxidase (LOX)." (PMID 30927930, 2019). "Another study showed that TNF-α can promote transendothelial migration of breast cancer via upregulation of LOX." (PMID 31341911, 2019). "In models of breast cancer, bone marrow-derived MSCs promote de novo lysyl oxidase (LOX) production from breast tumor cells, this in turn stimulates Twist transcription and triggers EMT." (PMID 31569731, 2019). "LOX is highly expressed in hypoxic tumour cells, including breast cancer, where it promotes extracellular matrix remodelling in the lungs, leading to the formation of a metastatic niche." (PMID 30813438, 2019). "Other previous investigations that focused mostly on breast carcinomas, identified that LOX can induce migration and invasion of malignant breast epithelial cells." (PMID 31636853, 2019). "It was demonstrated that DTCs derived from breast cancer cell secrete collagen crosslinking enzyme LOX and PLOD2, thereby amplifying focal adhesion signaling mediated by integrin by stiffening ECM45,46." (PMID 31882647, 2019). "We demonstrated that expression of LOX, the gene with the highest level of induction in biomimetic scaffolds, has prognostic value in breast cancer patients, being significantly higher in the primary tumor of patients that developed metastatic disease." (PMID 31439905, 2019). "siRNA knockdown of LOX or inhibition with BAPN in human MDA-MB-231 breast cancer cells reduced hypoxia-driven invasion in nude mice, demonstrating a clear role for LOX in hypoxia-driven metastasis." (PMID 29098360, 2018). "In breast cancer cells, endogenous LOX and LOXL2 expression has been shown to be upregulated when the cells were incubated with fibroblast-conditioned medium or plated on a fibroblast-conditioned collagen matrix." (PMID 30701028, 2018). "The application of a LOX-directed antibody, which is capable of inhibiting enzymatic function, in a mouse model of breast cancer resulted in decreased number of pre-metastatic osteolytic lesions." (PMID 29755969, 2018).
breast carcinoma (continued). "Their study using spontaneously metastasizing ER- breast cancer 4T1 cells, which express high levels of LOX, demonstrated that inhibition of LOX by short hairpin RNA or anti-LOX antibody abrogates bone metastasis formation." (PMID 30423905, 2018). "LOXL2 has similar biological activities in ECM remodeling as LOX, and its overexpression indicates poor prognosis in patients with colon and esophageal squamous cell carcinoma, as well as gastric cancer and breast cancer." (PMID 29728125, 2018). "Experiments in vitro showed that LOX overexpression promotes breast cancer invasion, metastasis and epithelial-to-mesenchymal transition (EMT)." (PMID 30237810, 2018). "This indicates that both procollagen secretion (P4H related) and further triple-helical molecules crosslinking (LOX related) are important regulatory processes for breast cancer lung metastasis." (PMID 30181809, 2018). "Lastly, as a validation of this model for future screen of therapeutic agents, we demonstrated that LOX inhibitor exhibited a significant decrease in breast cancer cell viability, migration, and EMT." (PMID 30181809, 2018). "LOX is related to the poor prognosis in breast cancer, lung cancer, colorectal cancer, uveal melanoma, pancreatic cancer, gastric cancer, and laryngeal cancer." (PMID 29472856, 2018). "HMGA2 inhibition after ectopic RKIP induction in breast cancer cell lines resulted in induction of miR200b, which in turn downregulated its direct target LOX, thus leading to decreased tumor cell invasion and metastasis." (PMID 30149591, 2018). "The role of LOX expression can be crucial, as lung metastases in a breast cancer model were shown to be dependent on LOX-driven fibrosis." (PMID 29362402, 2018). "Recently, we have shown that hypoxia increases expression and release of lysyl oxidase (LOX) from primary mammary tumours, which in turn disrupts bone homeostasis to favour osteolytic degradation to create pre-metastatic niches in the bone microenvironment." (PMID 29098360, 2018). "We demonstrated that LOX secreted by a distal mammary tumours triggered osteolytic bone lesion formation." (PMID 29098360, 2018). "We found that when LOX was depleted in MDA-MB-231 breast cancer cells grown in standard plastic (2D) culture conditions, phosphorylation of several RTKs including the EGFR was reduced." (PMID 28416796, 2017). "LOX-mediated cross-linking has been proposed to promote breast cancer malignant progression by increasing ECM stiffness." (PMID 28423580, 2017). "Recent studies showed that multiple hypoxia-HIF signaling pathways promote breast cancer metastasis by inducing the expression of LOX." (PMID 28356139, 2017). "LOX is highly expressed in hypoxic breast cancer cells and related to the invasive and metastatic potential of breast cancer by modulating focal adhesion kinase (FAK) activity and cell-ECM adhesion." (PMID 28356139, 2017). "Mapping of gene expression signatures in breast cancer cell lines has noted ATP7A as well as LOX as upregulated genes." (PMID 28425924, 2017). "While LOX-PP was described as a Ras tumor suppressor, reversing mesenchymal tumor cells to a more epithelial phenotype, the LOX enzyme was found to facilitate a more migratory and invasive phenotype during breast cancer progression." (PMID 28143503, 2017). "A previous study reported that LOX is highly expressed in highly invasive cancers and metastatic breast cancer cell lines." (PMID 29261141, 2017). "Dual LOX / LOXL2 inhibition (PXS-S1A) showed a greater degree of inhibition supporting previous studies on the role of LOX in breast cancer primary tumor growth." (PMID 28199967, 2017). "In breast cancer, LOX appears to facilitate cancer cell migration and adhesion through hydrogen peroxide-mediated regulation of FAK/Src signaling." (PMID 26882568, 2016). "Inhibition of LOX has been found to suppress the establishment of lung and liver metastases in an orthotopic breast cancer model." (PMID 26804196, 2016).
breast carcinoma (continued). "Based on these findings, we suggest that bisphosphonates are potentially effective chemotherapeutics for treating LOX+ ER– breast cancer patients." (PMID 27147578, 2016). "Given that MMP2, COL1A1 and SPARC are all pro-metastatic genes, we suggest these genes play crucial roles in LOX+ breast cancer metastasis." (PMID 27147578, 2016). "We address that issue in the present study and show the significant prognostic power of LOX in ER– breast cancer." (PMID 27147578, 2016). "In a breast cancer model, inhibition of LOX reduced the formation of liver and lung metastases but did not affect orthotopic tumour growth." (PMID 26804196, 2016). "Lysyl oxidase secreted by tumor endothelial cells promotes angiogenesis and metastasis in colorectal cancer and breast cancer." (PMID 28036074, 2016). "Upregulated LOX-mediated ECM remodeling is a poor prognostic marker in breast cancer and head and neck cancer." (PMID 27966444, 2016). "LOX is upregulated in invasive breast cancer cell lines and breast carcinomas and has been shown to facilitate breast cancer cell migration by regulating cell-extracellular matrix adhesion formation." (PMID 26908052, 2016). "LOX inhibitors such as beta-aminopropionitrile (BAPN) have been shown to reduce breast cancer cell motility in vitro." (PMID 27275004, 2016). "HMGA2 dysregulation is correlated with poor survival for patients with CRC and promotes breast cancer metastasis by increasing LOX expression." (PMID 26968810, 2016). "Hypoxic breast cancer cells release an amine oxidase, lysyl oxidase (LOX) that accumulates at sites of pre-metastatic niche formation." (PMID 27092178, 2016). "In the present bioinformatics study, we observed that LOX is a prognostic factor for poor progression free survival in patients with ER– breast cancer." (PMID 27147578, 2016). "LOX is overexpressed in various tumors such as oral cancer, tumor endothelial cells, gastric cancer, breast cancer, and anaplastic thyroid cancer (ATC)." (PMID 28036074, 2016). "LOX/LOX-L expression correlates with worse prognosis in head and neck, lung, ovarian and breast cancers." (PMID 27275004, 2016). "Although our findings suggest that osteoblast-derived LOX does not affect metastatic prostate cancer cell migration, tumor-derived LOX participates in the progression of osteolytic bone metastasis in breast cancer." (PMID 26567111, 2016). "Elevated LOX levels in breast cancer positively correlate with invasiveness and reduced metastasis-free and overall survival." (PMID 26908052, 2016). "LOX expression correlates with the level of tissue hypoxia, and it is known to play a critical role in breast cancer metastasis." (PMID 26265048, 2015). "Because HMGA2 regulates LOX expression, we continued to detect the downstream effectors of LOX in breast cancers." (PMID 25919570, 2015). "Recent reports in the literature and the present TMA analytical data confirm that LOX is a suitable molecular target for breast cancer therapy." (PMID 26265048, 2015). "The high levels of LOX in breast cancer and its important role during metastasis make it an important target for non-invasive molecular imaging in vivo." (PMID 26265048, 2015). "Hypoxic breast cancer cells also express higher levels of LOX, as demonstrated in a previous study with human MDA-MB-231 cells." (PMID 26265048, 2015). "Clinically, breast cancer patients with ER-negative tumours and overexpression of LOX have poor survival." (PMID 26472542, 2015). "Mice with fibrotic lungs and livers had an increased number of spontaneous 4T1 breast cancer metastases to these organs, which was abrogated by blocking LOX activity." (PMID 26539408, 2015). "Previous studies have demonstrated LOX-mediated collagen crosslinking promotes breast cancer progression." (PMID 26585689, 2015). "Recently, LOX, secreted by tumor epithelial cells, was also shown to induce pre-metastatic bone lesions that precedes and facilitates the formation of breast cancer metastases." (PMID 26501565, 2015).